LGI1 (leucine rich glioma inactivated 1)
Diseases named in the same sentence as LGI1 in open-access papers (continued):
Sharing a sentence is not in itself a finding about the gene and the disease.
encephalitis (continued). "In contrast, GABAA-R autoantibodies have been found in severe forms of encephalitis e.g., in combination with anti-LGI1 in a patient presenting a subacute onset of memory loss, confabulation, and behavioral changes." (PMID 31557990, 2016). "Because of the high suspicion of anti-LGI1 encephalitis and exclusion ofalternative causes, empiric treatment with high dose intravenous methylprednisoloneand immunoglobulin was performed while awaiting diagnostic tests." (PMID 29213481, 2016). "By proposing a novel metabolic pattern, our findings may provide imaging‐based evidence to support the clinical utility of PET in anti‐LGI1 encephalitis and offer new insights into its underlying pathophysiological mechanisms." (PMID 41399525, 2025). "However, decision-making on the recurrence in patients with anti-LGI1 encephalitis remains a diagnostic conundrum, especially in patients with substantial cognitive sequelae." (PMID 41164023, 2025). "Background and Aims: Encephalitis associated with antibodies against Leucine‐rich glioma inactivated 1 protein (LGI1) commonly manifests with cognitive impairment, psychiatric symptoms, and epileptic seizures, including the pathognomonic faciobrachial dystonic seizures (FBDS)." (PMID 40542608, 2025). "Consequently, the causal influences underpinning brain circuits in anti-LGI1 encephalitis remain elusive." (PMID 40919049, 2025). "Interestingly, FBDS, a hallmark clinical feature of anti-LGI1 encephalitis, was identified in only 16.1% (14/87) of patients in our cohort, which is notably lower than the 30–50% reported in previous studies." (PMID 41473232, 2025). "This sample was drawn from a 60-year-old man with a typical clinical presentation of anti-LGI1 aAbs encephalitis associating temporal seizures, confusion with spatial temporal disorientation, and left temporal Flair hyperintensities on magnetic resonance imaging (MRI)." (PMID 40303411, 2025). "Notably, Patient 7 presented with faciobrachial dystonic seizures (FBDS), a phenotype typically associated with anti-LGI1 encephalitis, highlighting the potential for overlapping symptoms." (PMID 41280886, 2025). "Collectively, these findings introduce a novel, noninvasive biomarker for early detection, risk stratification, and monitoring of anti‐LGI1 encephalitis, while offering fresh insights into the metabolic mechanisms underlying pathogenesis of clinical manifestations." (PMID 41399525, 2025). "Additionally, the DRB1*08:03 ~ DQB1*06:01 or B*08:01 ~ C*07:02 haplotype was likely to be associated with anti-LGI1 encephalitis." (PMID 39820999, 2025). "Importantly, the identified z‐score pattern correlated positively with both the mRS and the CASE score, underscoring its potential utility for risk stratification in acute anti‐LGI1 encephalitis." (PMID 41399525, 2025). "Therefore, subcortical shape analysis not only enhances our understanding of the neuroanatomical damage associated with anti-LGI1 encephalitis but also offers valuable tools for improving diagnosis, monitoring, and treatment strategies." (PMID 40688080, 2025). "Despite advances in understanding the effective connectivity (EC) of brain networks in leucine-rich glioma-inactivated 1 (LGI1) antibody encephalitis, the specific cause and underlying mechanisms of LGI1 encephalitis remain unclear." (PMID 40919049, 2025). "To gain further insight into direct intrathecal pathogenic effects of autoantibodies in LGI1-Ab encephalitis we infused CSF-cell-derived anti-LGI1 mAbs into the brains of both mice and rats and explored the in vivo behavioral, structural, and epileptogenic effects." (PMID 39984135, 2025). "Anti-LGI1 encephalitis is an autoimmune encephalitis caused by autoantibodies against LGI1." (PMID 41164023, 2025).
encephalitis (continued). "In summary, this case highlights the critical importance of maintaining a high level of clinical suspicion for AE, particularly LGI1 antibody-associated encephalitis, in older adults who present with subacute neuropsychiatric symptoms and atypical seizure activity." (PMID 40718213, 2025). "Due to the unusual association of LGI1 antibodies with tumors and the unavailability of tissue to be tested for expression of LGI1 antigens, as recommended in atypical cases, we cannot exclude a coincidental association between the encephalitis and the lung adenocarcinoma." (PMID 40407616, 2025). "Anti-LGI1 encephalitis is associated with disruptions in large-scale brain network functionality." (PMID 40688080, 2025). "For instance, LGI1-associated encephalitis has shown hippocampal atrophy in follow-up MRI brain." (PMID 39376559, 2024). "In our study, 23.81% (5/21) of patients with anti-LGI1 encephalitis experienced prodromal symptoms such as piloerection, loss of consciousness, visual abnormalities, upper abdominal discomfort, and sensory disturbances before seizures; 14.29%(3/21) exhibited FBDS." (PMID 39539648, 2024). "Leucine-rich glioma-inactivated 1-antibody-encephalitis is a treatable and potentially reversible cause of cognitive and psychiatric presentations, and may mimic cognitive decline, rapidly progressive dementia and complex psychosis in older patients." (PMID 38699852, 2024). "Anti-LGI1 encephalitis is commonly associated with temporal lobe onset seizures." (PMID 39539648, 2024). "Motor phenomena associated with anti-LGI1 encephalitis in this case included hyperkinetic FBDS, which might be related to the observed MRI abnormalities in both the right caudate nucleus and temporal lobe." (PMID 37033571, 2023). "N-methyl-d-aspartate receptor (NMDAR) antibody-associated encephalitis was first identified in 2007, followed by leucine-rich glioma inactivated protein 1 (LGI-1) antibody-associated encephalitis and anti γ-aminobutyric acid type B receptor (GABABR) antibody-associated encephalitis." (PMID 37553563, 2023). "Consequently, AMPA-current dependent LTP is impaired, and this is thought to be the direct cause of memory impairment seen in patients with anti-LGI1 encephalitis." (PMID 38201219, 2023). "This raises the question whether epitope spreading may be one mechanism behind the evolution of symptoms in LGI1-associated encephalitis as seen in other autoimmune diseases." (PMID 36672216, 2023). "LGI1 antibody encephalitis has been associated with seizures, memory loss, and sleep disorders." (PMID 36755772, 2023). "In addition, IgG secreted in patients with anti-LGI1 encephalitis disrupts the LGI1 signal of presynaptic and postsynaptic neurons, causing neuronal hyperexcitability and reversible memory deficits." (PMID 37304289, 2023). "Therefore, the aim of this report was to describe a case of anti-leucine-rich glioma-inactivated 1 (anti-GLI1) encephalitis with a predominant psychiatric presentation that caused a delay in diagnosis and treatment and a chronification of cognitive impairment." (PMID 37275973, 2023). "Anti-LGI1 encephalitis is rarely associated with malignant neoplasms." (PMID 37033571, 2023). "Although the recognition of FBDS is critical to suspecting anti-LGI1-associated encephalitis, this specific pattern of involuntary movements may be absent in some patients." (PMID 37033571, 2023). "In addition, our research revealed that the poor prognosis of LGI1 encephalitis patients was associated with an increase in ICMA1 expression." (PMID 37644514, 2023). "With accumulative clinical experience and better access to antibody detection methods, we hope to reach a diagnostic consensus on limbic encephalitis and anti-LGI1 encephalitis in children to help guide clinicians to make sensible evaluations, diagnosis and tailored treatments." (PMID 37179544, 2023).
encephalitis (continued). "Besides, decrease of antibody with clinical improvement was also seen in other IgG4-ND such as anti-LGI1 encephalitis, CASPR2-associated syndromes and in IgG4-RD." (PMID 35958552, 2022). "LGI1 encephalitis is the second most common cause of AE after NMDAR encephalitis." (PMID 35844590, 2022). "Additionally, Subgroup analysis suggested that higher antibody titer was the risk factor for relapse in anti - LGI1 encephalitis." (PMID 35757705, 2022). "Although diencephalon, insular cortex, and other scattered neocortical regions can be involved, the mesial temporal limbic structures and basal ganglia are the two important regions affected in anti-LGI1 encephalitis, and they are associated with distinctive symptoms." (PMID 36348436, 2022). "In subgroup of anti-LGI1 encephalitis, higher antibody titer was the risk factors of relapse." (PMID 35757705, 2022). "In anti-LGI1 encephalitis, antibody titer was associated with the likelihood of relapse." (PMID 35757705, 2022). "In addition, some presentations are very evocative of a specific cause, such as faciobrachial dystonic seizures in anti-LGI1 encephalitis." (PMID 34925200, 2021). "This may be a good explanation for SD in patients with encephalitis associated with LGI1 antibody, which is often related to hypothalamic disorders." (PMID 34899696, 2021). "The AE mediated by these antibodies accounted for 10–20% of all types of encephalitis, and the most common subtype among them is anti-NMDAR encephalitis, which accounts for ~80% of AE, followed by LGI1 antibody-associated encephalitis (LGI1 AE) and anti-GABABR encephalitis." (PMID 32431657, 2020). "The results indicated that abnormal brain connectivity and microstructure in brain areas associated with memory, cognition and motion dysregulation circuits were related to the generic risk of anti-LGI1 encephalitis, which makes it a potential endophenotype for anti-LGI1 encephalitis." (PMID 32317923, 2020). "Detection of these products may help us to understand the associations of the microbiota–gut–brain axis and anti-LGI1 encephalitis comprehensively." (PMID 33193049, 2020). "Moreover, cell adhesion molecules associated with the Kv1 complex, including Caspr2, Contactin2, and LGI1, are target antigens in autoimmune diseases associated with hyperexcitability such as encephalitis, neuromyotonia, or neuropathic pain." (PMID 33374190, 2020). "tumors known to be associated with LGI1-encephalitis are bronchial carcinoma and thymoma." (PMID 30233481, 2018). "CASPR2- and LGI1-antibody associated encephalitis poses a particular diagnostic challenge." (PMID 29951031, 2018). "The primary symptoms of LGI1 antibody encephalitis include cognitive impairment (recent memory loss or spatial disorders), seizures (typically FBDS), hyponatremia, and sleep disorders, while serum titers (and occasionally cerebrospinal fluid) of LGI1 antibodies are increased." (PMID 29980179, 2018). "The secreted leucine-rich glioma inactivated 1 (LGI1) protein is an important actor for human seizures of both genetic and autoimmune etiology: mutations in LGI1 cause inherited temporal lobe epilepsy, while LGI1 is involved in antibody-mediated encephalitis." (PMID 26878798, 2016). "Moreover, anti-LGI1 encephalitis is associated with bradyarrhythmias, which may occur even in the interictal periods." (PMID 38194197, 2024). "Sleep disorders at the acute phase may increase the risk of relapse in anti - LGI1 encephalitis." (PMID 35757705, 2022). "In addition, we also found that advanced age and CSF abnormalities may be associated with poor prognosis in anti-LGI1 encephalitis, however, these prognostic factors still need further confirmation." (PMID 34168612, 2021). "Besides, the increase in Succinivibrio in both anti-LGI1 encephalitis and schizophrenia may be associated with psychiatric symptoms." (PMID 33193049, 2020).
encephalitis (continued). "Therefore, the results of our study indicate that the dysregulation of the functional connectivity in ACC might be associated with impaired cognitive control in anti-LGI1 encephalitis." (PMID 32317923, 2020). "For the first time, using DIRS, we demonstrate highly active intrathecal B-cell activity in LGI1 antibody patients and show that B-cell repertoires, particularly from postgerminal center B cells on both sides of the BBB, may actively mutate and mature in patients with LGI1 antibody encephalitis." (PMID 32029531, 2020). "In patients with anti-LGI1 Ab-mediated encephalitis, we identified hippocampal swelling on initial MRI to be associated with worse function at 12 months (OR 0.03; 95% CI 0.003, 0.34; P = 0.005)." (PMID 42318510, 2026). "The first AE GWAS with discovery and validation cohorts took place in leucine-rich glioma-inactivated 1-antibody encephalitis (LGI1-Ab-E)." (PMID 42007814, 2026). "In anti-LGI1 Ab-mediated encephalitis, both hippocampal swelling (OR 5.76; 95% CI 1.14, 29.02; P = 0.03) and T2/FLAIR hyperintensity (OR 6.81; 95% CI 1.28, 36.22; P = 0.03) were related to the development of mesial temporal atrophy and hippocampal sclerosis." (PMID 42318510, 2026). "Previous studies have primarily focused on blood sodium levels, revealing that hyponatremia is a common feature of anti-LGI1 encephalitis." (PMID 40352922, 2025). "To gain precise understanding of subtle subcortical structural alterations, we employed shape analysis which is capable of capturing localized shape deformations in anti-LGI1 encephalitis using high-resolution anatomical MRI data." (PMID 40688080, 2025). "We conducted a retrospective study of 87 patients diagnosed with anti-LGI1 encephalitis during the acute phase, admitted to two tertiary hospitals in China between January 2022 and September 2024." (PMID 41473232, 2025). "In the context of anti-LGI1 encephalitis, the hyperexcitability of the hippocampus due to autoimmune effects on LGI1 has emerged as a primary target of this disease." (PMID 40688080, 2025). "Seven (39%) patients were diagnosed with specific encephalitis syndromes, including two with LGI1-Ab encephalitis who were treated successfully within current guidelines and made good recoveries." (PMID 39985693, 2025). "Anti-leucine-rich glioma-inactivated-1 (LGI1) encephalitis is an autoimmune disorder characterized by antibodies that target LGI1 (LGI1-IgG)." (PMID 40703404, 2025). "Refractory hyponatremia is a frequent complication of anti‐LGI1 encephalitis, often persisting despite conventional sodium replacement." (PMID 41399525, 2025). "A recent rat model utilizing the direct inhibition of Kv1.1 currents by dendrotoxin-K (DTX-K) in the primary motor cortex recapitulated the seizures observed in patients with LGI1-Ab encephalitis including FBDS." (PMID 39984135, 2025). "There were 31 patients with anti-LGI1 encephalitis (22 males and 9 females; mean age 54.9 ± 13.6 years) and 31 normal controls (20 males and 11 females; mean age 52.9 ± 11.3 years)." (PMID 40688080, 2025). "We herein report the case of a 67-year-old man who developed subacute parkinsonism following serial COVID-19 vaccination, with anti-LGI1 encephalitis emerging as a potential mediating factor." (PMID 41311428, 2025). "The patient was diagnosed with anti-LGI1 encephalitis based on high signal intensity on fluid-attenuated inversion recovery in the medial temporal lobes and antibody test results." (PMID 41164023, 2025). "As of the last follow-up on March 1, 2025, clinical data from 87 patients with anti-LGI1 encephalitis were analyzed." (PMID 41473232, 2025). "Functional MRI (fMRI) studies have revealed alterations in brain function in anti-LGI1 encephalitis patients, using functional connectivity to evaluate brain networks." (PMID 40919049, 2025).
encephalitis (continued). "To explore metabolic correlates of FBDS, we stratified the anti‐LGI1 encephalitis patients into two subgroups based on the presence or absence of FBDS: the FBDS group and the non‐FBDS group." (PMID 41399525, 2025). "We observed inward shape deformations in the shell of the NAc in patients with anti-LGI1 encephalitis compared with healthy controls." (PMID 40688080, 2025). "Anti‐leucine‐rich glioma inactivated 1 (anti‐LGI1) autoimmune encephalitis is a rare subtype of encephalitis that usually manifests as limbic encephalitis." (PMID 41399525, 2025). "Typical clinical features of anti-LGI1 encephalitis include frequent epileptic seizures, mainly faciobrachial dystonic seizures (FBDS), cognitive decline, psychiatric-behavioral abnormalities, and autonomic dysfunction such as hyponatremia." (PMID 40519939, 2025). "FBDS, which is believed to be a specific manifestation of anti-LGI1 encephalitis, was observed in only three cases." (PMID 40958893, 2025). "First, by leveraging 18F‐FDG PET, we comprehensively characterized both global metabolic patterns and regional covariance networks in the acute phase of anti‐LGI1 encephalitis." (PMID 41399525, 2025). "T2/FLAIR hyperintensities and volume atrophy within the hippocampus, including its subregions such as cornu ammonis 2/3 (CA2/3) and CA4/dentate gyrus, have been consistently observed in patients with anti-LGI1 encephalitis." (PMID 40688080, 2025). "A recent German case series (n = 8) described rapid mRS improvement after efgartigimod rescue in steroid‐refractory anti‐LGI1 encephalitis." (PMID 40785430, 2025). "In the literature, anti-mGluR2 antibody-positive encephalitis is characterized by cerebellar ataxia, while anti-LGI1 antibody-positive encephalitis is characterized by limbic symptoms." (PMID 40519939, 2025). "Statistical analysis confirmed significant functional improvement after immunotherapy (p < 0.001), indicating a generally favorable prognosis in anti-LGI1 encephalitis." (PMID 41473232, 2025). "In anti‐LGI1 encephalitis, unilateral or bilateral medial temporal hypermetabolism, most pronounced in the hippocampus, often coexists with basal ganglia metabolic abnormalities." (PMID 41153078, 2025). "It is noteworthy that anti-LGI1 encephalitis differs from other more common forms of AE, such as anti-NMDAR encephalitis and paraneoplastic encephalitis, in terms of clinical presentation, laboratory findings, and neuroimaging features." (PMID 41473232, 2025). "This study provides a comprehensive 18F‐FDG PET‐based assessment of whole‐brain metabolism in the acute phase of anti‐LGI1 encephalitis." (PMID 41399525, 2025). "A typical example is autoimmune limbic encephalitis, which frequently presents as anti-NMDA receptor encephalitis or anti-LGI1 encephalitis." (PMID 41306289, 2025). "Three patients (one patient with anti-NMDAR encephalitis and two patients with anti-LGI1 encephalitis) were lost to follow-up, and 80 patients remained in the study group." (PMID 40977726, 2025). "Previous studies have documented hippocampal atrophy and impaired microstructural integrity in anti-LGI1 encephalitis." (PMID 40919049, 2025). "In this study, we employed spDCM methods to examine the effective connectivity patterns in anti-LGI1 encephalitis patients." (PMID 40919049, 2025). "For instance, patients diagnosed with anti-LGI1 encephalitis frequently respond better to corticosteroids than to IVIG." (PMID 40131535, 2025). "Prognostic features are best characterised for anti-NMDAR and anti-LGI1 encephalitis, though recently, increased attention has been given to the study of antibody-negative disease, albeit limited by methodological challenges." (PMID 40281286, 2025). "With respect to 18F-FDG PET/CT, previous studies and case reports have demonstrated that anti-LGI1 encephalitis frequently presents with hypermetabolism in the basal ganglia and/or medial temporal lobes, a pattern consistent with the results of this study." (PMID 41473232, 2025).